NLRP3 (NLR family pyrin domain containing 3)
Diseases named in the same sentence as NLRP3 in open-access papers (continued):
Sharing a sentence is not in itself a finding about the gene and the disease.
Hepatitis (continued). "The disruption of HSF1 reduced Snail activation and enhanced NLRP3 activation, while the adoptive transfer of HSF1-expressing macrophages to Notch1M-KO mice augmented Snail activation and mitigated IR-triggered liver inflammation." (PMID 31673056, 2020). "The results of Qiu T and others showed that taurine supplementation could reduce the protein expression of NLRP3, ASC and Caspase-1 in liver tissue in an arsenic trioxide (AS2O3)-induced mouse hepatitis model." (PMID 38560269, 2024). "The results of this study indicate that MA could inhibit the levels of NLRP3 inflammasomes, reduce HFD-induced liver inflammation, induce M2-type polarization of macrophages and alleviate metabolic inflammation, but the mechanism requires further study." (PMID 36834674, 2023). "Indeed, NLRP3-selective inhibitors such as MCC950 and NR1D1 have shown to reduce inflammation levels in these mice models, consequently preventing hepatitis in the liver." (PMID 34281264, 2021). "We have determined that NLRP3 inflammasome played an important role in ConA-induced hepatitis, but the mechanism of NLRP3 inflammasome activation has not been demonstrated." (PMID 29692782, 2018). "In conclusion, our results demonstrated that NLRP3 inflammasome-dependent IL-1β production was crucial in the pathogenesis of ConA-induced hepatitis, which shed light on the development of promising therapeutic strategies for AIH by blocking NLRP3 inflammasome and IL-1β." (PMID 29692782, 2018). "We hypothesized that not only hepatitis and consequent fibrosis but also liver steatosis in the progression of NASH may be triggered or modulated by NLRP3 inflammasome activation." (PMID 30140364, 2018). "Among these cytokines, TNF-α and IL-1β could be the critical mediators for development of ConA-induced hepatitis, since TNF-α-deficient mice and NLRP3- and caspase-1-deficient mice that do not produce IL-1β are almost protected from ConA-mediated liver damage." (PMID 33809904, 2021). "Upon sensing noxious signals, NLRP3 recruits pro-caspase-1 and the adaptor molecule ASC (apoptotic specklike protein-containing CARD), resulting in activation of caspase-1 as well as secretion of IL-1β and interleukin-18 (IL-18), which play a critical role in promoting liver inflammation." (PMID 29692782, 2018). "In conclusion, NLRP3 was involved in BU/CY-induced liver inflammation after HSCT and selectively inhibited it ameliorated liver inflammation and improved liver function, suggesting targeting NLRP3 might be a new approach in the prophylaxis of liver inflammation after HSCT." (PMID 26635145, 2015).
neonatal-onset multisystem inflammatory disease (56 papers, 2011 to 2025). "The father carried a genetic mutation associated with CINCA syndrome/NOMID (NLRP3 c.2068G>A p.Glu690Lys Hetero), which was also found in the child." (PMID 38808101, 2024). "NOMID (neonatal-onset multisystem inflammatory disease) patients suffer from a severe auto-inflammatory disease caused by activating mutations of the NLRP3 gene, and knock-in mice with a NOMID mutation show a similar phenotype." (PMID 37771587, 2023). "Taking advantage of this feature, NLRP3-mutant and wild-type (WT) iPSCs were established from patients with CINCA syndrome harboring a somatic NLRP3 mutation." (PMID 35603217, 2022). "CAPS includes three phenotypes, progressively more severe: FCAS, MWS and CINCA syndrome, all representing the same autosomal-dominant disease spectrum, caused by NLRP3 mutations." (PMID 35883675, 2022). "The NLPR3 inflammasome is an attractive drug target because NLRP3 inflammasome activation is associated not only with rare autoinflammatory disorders such as CINCA syndrome but also with the pathogenesis of various chronic inflammatory conditions." (PMID 35603217, 2022). "A 42-year-old female was diagnosed with DFNA34, a non-syndromic form of hearing loss due to an NLRP3 variant residing in the LPR domain possibly with lower pathogenic potential than CINCA syndrome." (PMID 34580346, 2021). "Here, we present three cases representing each of the three categories of autoinflammatory inner ear disorder (CINCA syndrome/DFNA34/AID) which exhibited distinct MRI features according to the genotypes of NLRP3 variants." (PMID 34580346, 2021). "Taking advantage of this feature, NLRP3-mutant and wild-type iPS cells were established from CINCA syndrome patients with a somatic NLRP3 mutation." (PMID 33535645, 2021). "FCAS2 arises from pathogenic variants in NLRP12, while MWS, FCAS1, and CINCA syndrome can be attributed to gain-of-function pathogenic variants in the NLRP3 gene." (PMID 33396879, 2020). "Patients affected by CINCA/NOMID syndrome and carrying germinal mutation in NLRP3 gene have the chance of 50% to transmit the disease to each child, since the modality of transmission is autosomal dominant." (PMID 27927236, 2016). "To model the human NOMID syndrome and to achieve insights into its associated skeletal abnormalities, we generated mice globally expressing the D301N mutation in Nlrp3, corresponding to the D303N mutation in human NLRP3, linked to NOMID." (PMID 22558291, 2012). "Among different inflammasomes identified so far, NLRP3 is of main interest since mutations in Nlrp3 gene are associated with autoinflammatory diseases such as Muckle–Wells syndrome, neonatal onset multisystem inflammatory disease, and familial cold urticaria/autoinflammatory syndrome." (PMID 31892810, 2019). "Interestingly, a mutation at Tyr 861 (Tyr -> Cys) in NLRP3 has been reported as causative for neonatal-onset multisystem inflammatory disease (NOMID), a form of CAPS, further supporting the hypothesis that phosphorylation at this site is necessary for restraint of inflammasome activation." (PMID 38763335, 2024). "Neonatal-onset multisystem inflammatory disease (NOMID) is a rare and severe autoinflammatory disease caused by mutations of the NLRP3 gene and is characterized by a skin rash, fever, arthropathy, and neurologic manifestations." (PMID 38250066, 2023). "Additionally, other NLRP3-associated hereditary autoinflammatory syndromes from the group of cryopyrin-associated periodic syndromes including Muckle-Wells-Syndrome, familial cold autoinflammatory syndrome and chronic infantile neurological cutaneous articular syndrome have been classified." (PMID 36911693, 2023). "They created a model of neonatal-onset multisystem inflammatory disease (NOMID), a rare disease caused by a mutation in the NLR family pyrin domain-containing 3 (NLRP3) gene encoding protein cryopyrin." (PMID 35159338, 2022).
neonatal-onset multisystem inflammatory disease (continued). "Of the four patients clinically diagnosed with CINCA syndrome/DFNA34, three were confirmed to have an NLRP3 variant based on genetic testing." (PMID 34580346, 2021). "CINCA syndrome is a rare AIED with autosomal dominant inheritance, and is linked with NLRP3 variants which cause hyper-activation of inflammasomes and excessive release of interleukin-13." (PMID 34580346, 2021). "NLRP3 is involved in most forms of inflammation—notably in gout, and also in certain diseases such as cold-induced auto-inflammatory disease, or neonatal onset multisystem inflammatory disease (NOMID)." (PMID 27487306, 2016). "However, overproduction of IL-18/1β and NLRP3 leads to neonatal-onset multisystem inflammatory disease (NOMID) which damages the spleen, skin, liver, and bone a lot." (PMID 36091247, 2022). "Mutations in and around the NACHT of NLRP3 cause three auto-inflammatory diseases: FCAS (familial cold auto-inflammatory syndrome), MWS (Muckle–Wells Syndrome), and CINCA/NOMID (chronic infantile neurological cutaneous and articular syndrome/neonatal onset multisystemic auto-inflammatory disease)." (PMID 33997004, 2021). "The genetics of CINCA syndrome are characterized by the presence of NLRP3 mutations as low frequency somatic mosaicisms rather than constitutive in about 30–40% of patients." (PMID 33535645, 2021). "Diagnosis was initially unclear and she underwent genetic testing for neonatal onset multisystem inflammatory disease (CINCA syndrome) which did not identify any pathogenic variants in NLRP3, furthermore histology of synovial fluid revealed a non-inflammatory picture, thus not consistent with CINCA." (PMID 35717242, 2022). "Therefore, we established iPS cells from a patient with CINCA syndrome who did not have the NLRP3 mutation, induced them to differentiate into macrophages, and confirmed the production of IL-1β." (PMID 33535645, 2021). "Furthermore, NLRP3 was below detection limits in ex vivo macular RPE from AMD patients, as well as in human induced pluripotent stem cell (hiPSC)-derived RPE from patients with overactive NLRP3 syndrome (Chronic infantile neurologic cutaneous and articulate, CINCA syndrome)." (PMID 29323137, 2018).
silicosis (56 papers, 2009 to 2026). Silicosis is a respiratory disease caused by breathing in (inhaling) silica dust. "Overall, these findings highlight for the first time the potential of inflammasome-related markers, such as NLRP3 expression levels and inflammasome-associated cytokines, as diagnostic or prognostic biomarkers for silicosis." (PMID 40119408, 2025). "Its activation through the NLRP3 inflammasome axis is quoted to cause LF and silicosis besides stimulating cytokines like IL-1β and IL-18 in silica-imparted human mesenchymal stem cells." (PMID 40504442, 2025). "NLRP3 deficiency limited subsequent pulmonary damage and fibrosis, including silicotic nodule formation at a more advanced stage of silicosis." (PMID 40119408, 2025). "A limited number of studies have implicated an in vivo role for NLRP3 in silicosis, with gene-deficient mice displaying reduced gross tissue pathology, including inflammation and fibrosis at 2–3 months." (PMID 40119408, 2025). "As previously shown, the deficiency of Nlrp3/Caspase-1/Gsdmd pathway cannot block silicosis, suggesting that IL-1β has a more fundamental role in silicosis." (PMID 36459518, 2022). "NLRP3 and its downstream factors, caspase-1, IL-1β, and IL-18, were greatly expressed in the lung tissue of rats with silicosis, while the inhibition or deficiency of NLRP3 alleviated EMT in lung epithelial cells or inflammation in macrophages." (PMID 34360876, 2021). "NLRP3 inflammasome activation and resultant IL-1β production by AMs is recognized as a significant mechanism underlying silicosis." (PMID 26913035, 2016). "Activation of the NLRP3 inflammasome has been linked with pulmonary fibrotic diseases, such as silicosis and asbestosis." (PMID 27527840, 2016). "Stem cell-based therapies have emerged as a promising therapeutic modality for silicosis, leveraging their inherent biological properties to target key pathogenic cascades, such as NLRP3 inflammasome activation, TGF-β1/Smad-mediated fibrotic progression, and Th1/Th2 immune homeostasis imbalance." (PMID 41789067, 2026). "Accumulating evidence has implicated a role for NLRP3 in silicosis pathogenesis." (PMID 40119408, 2025). "NLRP3 inflammasomes in macrophages are essential for silica recognition and initiated subsequent profibrotic events that have been implicated in the pathogenesis of silicosis." (PMID 34417574, 2022). "In spite of this, the molecular mechanism of NLRP3 activation in silicosis that causes lysosome damage remains unknown." (PMID 36131930, 2022). "This led to the finding that the decreased level of RAB20 in monocytes/macrophages may be strongly associated with NLRP3 inflammasome activation and the occurrence of silicosis." (PMID 36131930, 2022). "In vivo studies further validated that XFBD significantly downregulates the expression of NLRP3 and Cleaved-Caspase-1 proteins in the lung tissues of mice afflicted with silicosis." (PMID 41754797, 2026). "To further validate the role of bigelovin in inflammasome activation in vivo, we employed the murine silicosis model, an NLRP3‐dominant disease model." (PMID 40349158, 2025). "In this study, we investigated a role for NLRP3 in acute and chronic silicosis to provide clearer insights into pathogenesis and the potential of NLRP3 as a therapeutic target." (PMID 40119408, 2025). "Deletion of NLRP3 reduced the severity of these gross pathological features, implicating a role for NLRP3 in the chronic phase of silicosis." (PMID 40119408, 2025). "Bigelovin showed significant anti‐inflammasome efficacy in NLRP3‐related pulmonary disorders murine models of LPS‐induced ARDS and silicosis by inhibiting NLRP3 inflammasome activation." (PMID 40349158, 2025). "Abundant evidence suggests that NLRP3-mediated inflammation plays an essential role in the fibrogenesis and pathogenesis of silicosis." (PMID 38515835, 2024). "IL-1β is a downstream product of NLRP3 inflammasome activation and has pro-inflammatory and fibrinogenic effects in silicosis." (PMID 38515835, 2024).
silicosis (continued). "It is found that circRNA11:120406118|12040782 was increased in the peripheral serum of silicosis patients, which facilitated the progress of silicosis by aggravating NLRP3-mediated macrophages pyroptosis through sponging miR-30b-5p." (PMID 38601461, 2024). "Increasing evidence confirmed that NLRP3 inflammasome-mediated chronic inflammation participates in the development of silicosis." (PMID 37063430, 2023). "Oridonin suppressed particulate-induced NLRP3-independent cell death and IL-1α release and attenuated NLRP3-independent lung inflammation in a mouse model of silicosis." (PMID 37705538, 2023). "In a rat model of silicosis, silica was shown to activate the NLRP3 inflammasome and release of proinflammatory IL-1β, basic fibroblast growth factor, and high mobility group protein B1, resulting in silicosis." (PMID 36669831, 2023). "In macrophages and epithelial cells, silica-activated NLRP3 inflammasomes consisting of NLRP3, apoptosis-associated speck-like protein containing a CARD (ASC), and caspase-1 are essential for the development of silicosis." (PMID 35509892, 2022). "NLRP3 inflammasome activation, an important mechanism in the pathogenesis of silicosis, is activated by crystalline silica both in alveolar macrophages (AM) and airway epithelial cells." (PMID 35936059, 2022). "To evaluate the physiological relevance of Gsdmd, Gsdme and silicosis, we established experimental silicosis mouse model for WT, Nlrp3-/-, Caspase-1-/-, Gsdmd-/-, Gsdme-/- and Gsdmd-/-Gsdme-/- mice." (PMID 36459518, 2022). "Though the Nlrp3 inflammasome is involved in silicosis pathogenesis, inhibition of its classic downstream factors, Caspase-1 and Gsdmd, fails to block pyroptosis and cytokine release." (PMID 36459518, 2022). "Knockout of RAB20 induced severe silicosis development by significantly promoting NLRP3 inflammasome activation and IL-1β release." (PMID 36131930, 2022). "Among these, NLRP3 inflammasome activation that is part of the NOD-like receptor signaling pathway has been reported to participate in the pathogenesis of silicosis." (PMID 34417574, 2022). "According to single cell RNAseq analysis from control and silicosis murine lung tissue, it revealed that NLRP3 expression is mainly restricted to macrophages among 18 different cell populations." (PMID 34417574, 2022). "Pneumoconiosis induced by inhalation of silica and silicosis by long-term silica exposure is well-known to be regulated by the activation of NLRP3 inflammasome." (PMID 35415237, 2022). "Accumulating evidence shows that deregulated pulmonary NLRP3 immune signaling drives the development and progression of silicosis." (PMID 36131930, 2022). "BMSC treatment attenuated NLRP3 and caspase-1 expression, relieving lung inflammatory infiltrates and collagen deposition effectively in the silicosis rat model." (PMID 34360876, 2021). "The pathophysiology of silicosis includes deposition of silica particles in pulmonary alveoli accompanied by silica-mediated activation of the NLRP3 inflammasome in macrophages." (PMID 33534121, 2021). "For example, endocytosis of exogenous activators such as silica and asbestos by pulmonary macrophages results in NLRP3 inflammasome activation involving ROS and lysosome destabilization, in turn leading to silicosis and asbestosis, respectively." (PMID 27084336, 2016). "Phagocytosis of silica particles leads to NLRP3-inflamassome complex activation through lysosomal enzymes, culminating in IL-1β secretion, which participates in the acute and fibrotic processes of silicosis." (PMID 25310682, 2014). "In murine models of silicosis ASC-, NLRP3- and IL-1β-deficient mice are more resistant to the infiltration of inflammatory cells, the formation of granulomas, excess collagen deposition and the development of fibrosis in response to silica instillation." (PMID 25406505, 2014).